IL6 (interleukin 6)
Diseases named in the same sentence as IL6 in open-access papers (continued):
Sharing a sentence is not in itself a finding about the gene and the disease.
hepatocellular carcinoma (continued). "IL-6 is an important signaling molecule to affect immune system, lipid metabolism, insulin resistance, mitochondrial activity, and also promotes hepatocellular carcinoma (HCC) and melanoma progression." (PMID 32477009, 2020). "Another anti-inflammation and anti-tumor gene, heme oxygenase-1 (HO-1) is induced by Interleukin 6 (IL-6) through the IL-6/Janus kinase (JAK)/STAT3 pathways in hepatoma cells." (PMID 32545625, 2020). "Since HO-1 has anti-inflammatory characteristics, the IL-6-induced HO-1 seems to bring a balance in preventing cellular “over inflammation” in hepatoma cells." (PMID 32204510, 2020). "IL-6 promotes angiogenesis via IL-6/STAT3/VEGFA signaling in hepatocellular carcinoma, cervical cancer, and glioma carcinoma cells." (PMID 32993787, 2020). "To examine the effect of SMILE on IL-6-induced hepcidin expression in hepatocytes, we performed transient transfections with vectors expressing SMILE and hepcidin gene promoter in HepG2 cells, a human hepatoma cell line, and treated with IL-6." (PMID 32545266, 2020). "The aim of this study was to determine the potential crosstalk between HO-1 and IL-6, and to elucidate the signaling pathways involved in the induction of HO-1 by IL-6 in human hepatoma cells." (PMID 32204510, 2020). "We investigated the crosstalk between IL-6 and HO-1 in hepatoma cells, since IL-6 is known as one of the HO-1 stimulators." (PMID 32204510, 2020). "LncRNA NEAT1-containing paraspeckles also stimulate interleukin 6 (IL-6)-mediated hepatocellular carcinoma development by the nuclear entrapping of IL-6/signal transducer and activator of transcription 3 (STAT3) inhibitors." (PMID 32429086, 2020). "LncRNA-DILC inhibits the expression of IL-6 by binding to the IL-6 promoter DNA in hepatocellular carcinoma, thereby inhibiting the growth of cancer stem cells." (PMID 33537343, 2020). "Emerging evidence also indicates the hepatoma-intrinsic CCRK upregulates interlukin-6 (IL-6) production through EZH2/NF-κB signaling, which consequently induce MDSCs accumulation in TME." (PMID 31500650, 2019). "IL-6 can promote hepatocellular carcinoma (HCC) growth and metastasis via antagonism of TNF-α and IL-1β immune response." (PMID 31867004, 2019). "Autophagy has also been reported to promote invasion by activating Epithelial Mesenchymal Transition of hepatocellular carcinoma cells, by promoting secretion of factors like IL6, MMP2 and by activating the MAP kinase signaling pathway in glioblastoma cells." (PMID 30944042, 2019). "Rather, the impact of CRISPRa on RP11 and IL6 was examined in a different cell type, HuH-7, a hepatoma cell line widely used to study hepatocyte function." (PMID 31658298, 2019). "New findings suggest that IRE1α-XBP1 signaling promotes development of tumors such as hepatocellular carcinoma (HCC) or melanoma via upregulation of IL-6-driven Janus kinase-signal transducer and activator of transcription 3 (JAK-STAT3) signaling pathway." (PMID 31491919, 2019). "CAFs isolated from human hepatic carcinomas were shown to secrete IL-6, which activated STAT3 in DCs, resulting in generation of regulatory DCs." (PMID 31428105, 2019). "Hepatocellular carcinoma is a disease predominantly affecting males, which is due in part to the ability of estrogen to suppress IL-6." (PMID 31683879, 2019). "Interleukin-6 can activate the MAP3K upstream kinase MKK4 for the Jun N-terminal kinase (JNK) in human HepG2 hepatoma cells, a signaling pathway well known to regulate several normal biological processes, not solely stress-related responses." (PMID 31554244, 2019). "In human hepatoma cells (HepG2) Hy-IL-6 induces maximal expression of acute-phase proteins at molar concentrations that are substantially lower than those required when stimulating with IL-6." (PMID 31101051, 2019). "To confirm these findings, we treated hepatoma cells with surfen, which reduced IL6-induced stimulation of HAMP expression." (PMID 31315930, 2019).
hepatocellular carcinoma (continued). "The report about hepatocellular carcinoma demonstrated that IL-6, a CAFs-derived factor, was also reported to play an important role in the functions of dendritic cells through STAT3 signalling." (PMID 31462002, 2019). "In that study, the early stages of hepatocellular carcinoma showed the ability of MSCs to suppress liver cancer and reduce liver fibrosis and to employ anti-inflammatory effect via IL6 inhibition." (PMID 30346985, 2018). "However, despite its many positive effects, IL-6 is also associated with the development of hepatocellular carcinoma (HCC) after liver cirrhosis and elevated serum levels of IL-6 predict HCC progression in patients with chronic hepatitis B infection." (PMID 30423923, 2018). "In human hepatoma cells, gemcabene inhibited IL-6 plus IL-1β-induced CRP production in a concentration-dependent manner, reaching 70% inhibition at 2 mM." (PMID 29644527, 2018). "For example, SelP expression is downregulated by TNFα stimulation of 3T3-L1 cells, by IL-6 in human hepatoma cells, and studies of the human SelP promoter have shown it is responsive to IL-1β, IFNγ and TNFα in HepG2 cells." (PMID 30571741, 2018). "In the current study, we show that the CRP promoter is up-regulated by IL-6/ IL-1β or with IL-6 alone in a human hepatoma cell line." (PMID 29644527, 2018). "One study reported the secretion of IL6 by the BM-MSCs which activated IL6/Stat3 pathway promoting the invasion of the hepatocellular carcinoma cell line." (PMID 30346985, 2018). "The IL-6/JAK/STAT3 pathway has been shown to polarize macrophages toward the pro-tumoral M2 phenotype through activation of STAT3, and anti-IL-6 immunotherapy increased the number of M1 polarized macrophages in a hepatocellular carcinoma mouse model." (PMID 30766539, 2018). "This appears somewhat plausible in view of the C/EBPdown sequence shown to be involved in the gemcabene-mediated inhibition of IL-6-induced promoter activity in the transfected Alexander human hepatoma cells." (PMID 29644527, 2018). "For this, we prepared a double-stranded radiolabeled C/EBPup mutant and wild-type oligonucleotides to probe nuclear extracts isolated from Alexander human hepatoma cells, untreated or treated with IL-6 for 4 h (first 4 lanes)." (PMID 29644527, 2018). "Blockade of IL-6-induced STAT3 in hepatocellular carcinoma cell lines facilitates doxorubicin-mediated apoptosis in previously doxorubicin-resistant cells." (PMID 28186993, 2017). "TGF-β1 and IL-6 are predominantly produced by TAMs in hepatocellular carcinoma (HCC), which induce EMT and activate the STAT3 pathway, respectively, to promote liver CSC properties." (PMID 28337221, 2017). "Previous studies have shown IL-6 can regulate the expression of LncTCF7 in hepatocellular carcinoma via a STAT3 pathway." (PMID 28467474, 2017). "In summary, here we have demonstrated, using a hepatoma cell line, that IL-6 results in increased Cp levels and decreased Fpn1, indicating that the functions of these two proteins are not obligatorily linked together." (PMID 28118841, 2017). "In human neurons, GLS1 expression was upregulated by IL-1β or TNF-α treatment, and in a rat hepatoma model IL-6 or TNF-α treatment indirectly upregulated c-MYC expression." (PMID 28399896, 2017). "The present study identifies intracellular accumulation of MHBs as a transcription activator to stimulate hepatic and hepatoma cells to produce IL-6 through p38 MAPK/NF-κB pathways in an ER stress dependent manner." (PMID 27434097, 2016). "Meanwhile, L-02 cells secrete more IL-6 than hepatoma cells, and the same result was also observed in HBx-induced IL-6 production." (PMID 27434097, 2016). "Intestine-specific homeobox (ISX), a newly identified proto-oncogene, regulates cell proliferation and drives hepatocellular carcinoma (HCC) formation via cyclin D1 upregulation under stimulation by proinflammatory cytokines such as IL-6." (PMID 27175585, 2016).
hepatocellular carcinoma (continued). "IL-6 (interleukin 6) plays an important role in the development and growth of hepatocellular carcinoma (HCC) via both classic signaling and trans-signaling pathways." (PMID 27080032, 2016). "In hepatoma cells, IL-6-induced signal transducer and activator of transcription 3 (STAT3) activation facilitates viral gene transcription and is required for HCC formation and growth." (PMID 27434097, 2016). "Since hepatocellular carcinoma (HCC) development can be promoted by an inflammatory microenvironment, aberrant IL6 signaling is implicated in the onset of HCC." (PMID 26889381, 2016). "In HepG2 hepatocellular carcinoma cells, interleukin 6 (IL-6) induces STAT3-dependent miR-21 transcription." (PMID 26116372, 2015). "We found a significant negative correlation between miR23a and PGC1α expression, which concurs with recent evidence that miR23a inhibits PGC1α expression directly in hepatocellular carcinoma via the IL6-Stat3 signaling pathway." (PMID 25815108, 2015). "The IL-6/STAT3 signaling pathway also plays important roles in promoting the progression of hepatocellular carcinoma (HCC) by TAMs." (PMID 26016502, 2015). "The present study aimed to investigate the effect of AEG-1 on the proliferation and apoptosis of liver cancer cells and the role of IL-6 in this process using the HepG2 human hepatoma cell line." (PMID 24348829, 2014). "IL-6 induced expression of CDC25A in a STAT3-dependent manner in human hepatocellular carcinoma cells." (PMID 24743777, 2014). "We performed co-stimulation experiments with BMP6 and IL6 in human hepatoma (HuH7) cells, and measured the activity of a luciferase reporter gene driven by the hepcidin promoter 24 h after stimulation." (PMID 24391488, 2014). "STAT3 was found to bind to predicted STAT binding sequences within the JUNB promoter in response to IL-6 treatment in HepG2 hepatocellular carcinoma cells." (PMID 24743777, 2014). "Other studies find that miR-26a suppresses cell growth and metastasis through IL-6-Stat3 signaling in hepatocellular carcinoma." (PMID 24935220, 2014). "STAT3 has been shown to directly target the TIMP-1 gene as IL-6 has been observed to up regulate TIMP-1 levels in a STAT3-dependent manner in human hepatocellular carcinoma cells as well as human fibroblasts." (PMID 24743777, 2014). "The present study demonstrated that AEG-1 inhibition was able to reduce the secretion of IL-6 in hepatoma HepG2 cells." (PMID 24348829, 2014). "LGR is induced by interleukin-6, interleukin-1-beta and transforming growth factor-alpha in hepatoma cells, and is over-expressed in livers of the mice challenged by lipopolysaccharide, rendering it an acute phase protein." (PMID 24066001, 2013). "We also found that TNF-α inhibited both basal level and IL-6-induced hepcidin expressions in hepatoma cells." (PMID 24286116, 2013). "Previously, we demonstrated that tocilizumab completely blocked IL-6-induced hepcidin expression in hepatoma-derived cell lines, and it effectively improved AI by inhibiting hepcidin production in MCD patients." (PMID 24286116, 2013). "Recombinant CTRP3 reduced glucose output in cultured rat hepatoma cells by suppressing gluconeogenic genes, significantly inhibited LPS-induced IL-6 and TNF-α secretion in THP-1 cells, and reduced NF-κB p65 activity." (PMID 23409033, 2013). "Interleukin 6 (IL6) is an important cytokine produced during chronic hepatitis and is known to increase SPINK1 expression in hepatoma cell lines through an IL6 responsive element in the SPINK1 gene." (PMID 23527199, 2013). "In this study, we demonstrated that treatment of a hepatoma cell line with IL-6 or injection of IL-6 or LPS in mice decreased TMPRSS6 mRNA expression." (PMID 24376517, 2013). "To further assess the roles of TNF-α and IL-1β in the pathogenesis of RA-anemia and their effects on IL-6-induced hepcidin mRNA expression, we performed in vitro real-time RT-PCR assays using a hepatoma-derived cell line." (PMID 24286116, 2013).
hepatocellular carcinoma (continued). "The ability of IL-6 to decrease TMPRSS6 expression was also demonstrated in another human hepatoma-derived cell line, HepG2 cells." (PMID 24376517, 2013). "It has been reported that the expression of LRAG in human hepatoma cells was induced by IL-6, IL-1β, and TNFα; and that the LRAG expression was enhanced by the induction of acute inflammation in mice." (PMID 22568928, 2012). "For example, upon treatment of hepatoma cells and primary human macrophages with IL-6-type cytokines (e.g. IL-6 or OncostatinM) STAT1 phosphorylation can be observed but most of the phosphorylated STAT1 is rather trapped in STAT1/STAT3 heterodimeric complexes." (PMID 20719000, 2010). "Alternatively, Gharavi and El-Kadi (2005) showed in murine hepatoma cell lines that Cyp1a1 is down-regulated by the proinflammatory cytokines interleukin 1β (Il-1β), IL-6, and tumor necrosis factor α in an AHR-dependent manner." (PMID 19165387, 2009). "Among the many proinflammatory cytokines, recent report IL-6 mediates cell cycle arrest in hepatocellular carcinoma through a STAT 3-dependent pathway." (PMID 19707535, 2009). "The level of serum IL-6 has been reported to be elevated in patients with chronic hepatitis B, cirrhosis and hepatocellular carcinoma and represents the best marker of HBV-related clinical progression as compared with several other cytokines." (PMID 19374779, 2009). "In vitro studies in hepatoma cell lines illustrate the downregulation of Cyp3a11 exposed to the proinflammatory cytokines IL-6, IL-1β and TNF-α." (PMID 18059400, 2008). "Based on a previous report that IL-6 counteracts the growth inhibitory influence of TGF-β1 in a cultured hepatoma cell line, the possible role of IL-6 was examined in the present system." (PMID 17324269, 2007). "Further, a recent report using a cultured hepatoma cell line showed that IL-6 counteracted the growth inhibitory influence of TGF-β1, primarily through the activation of multiple anti-apoptotic signaling pathways." (PMID 17324269, 2007). "MYDGF may promote tumor angiogenesis and macrophage infiltration in hepatocellular carcinoma, releasing inflammatory cytokines, including IL-6 and TNF-α, which accelerate tumor progression." (PMID 40539074, 2025). "To determine whether the ACAP4 protein is essential for IL6-induced hepatoma cell migration, we knocked out ACAP4 in MHCC97H and HepG2 cells (ACAP4KO) via CRISPR-mediated technology." (PMID 39744421, 2025). "However, the involvement of the ACAP4‒ARF6 axis in interleukin-6 (IL6)-mediated hepatoma cell migration and its precise regulatory role in HCC metastasis remain to be elucidated." (PMID 39744421, 2025). "Furthermore, it has been implicated in the upregulation of pro-inflammatory cytokines such as IL-6, with studies showing that its suppression, e.g., by curcumin, reduces IL-6 expression and increases apoptosis in hepatocellular carcinoma cells." (PMID 40507021, 2025). "We found that IL6 promoted hepatoma cell migration at 6 and 12 h (p<0.01)." (PMID 39744421, 2025). "scRNA-seq analysis, induction of mouse KCs in vitro, and coculture of KCs with exosomes revealed that KCs serve as a significant source of IL6 production within the HCC TME following their differentiation into TAMs induced by exosomes derived from hepatoma cells." (PMID 39744421, 2025). "To further evaluate whether bufalin inhibits HCC tumor metastasis in vitro and in vivo by targeting JAK1-ACAP4, we performed wound healing and transwell migration assays to assess the inhibitory effect of bufalin on IL6-induced hepatoma cell migration." (PMID 39744421, 2025). "JAK1 promotes hepatoma cell migration in an ACAP4-ARF6-dependent manner in response to IL6." (PMID 39744421, 2025).
hepatocellular carcinoma (continued). "Dasatinib, an indirect STAT3 inhibitor, significantly facilitated anti-CTLA-4 immunotherapy in head and neck squamous cell carcinoma, while the combined blockade of IL-6 and PD-L1 remarkably inhibited the growth of pancreatic ductal adenocarcinoma and hepatocellular carcinoma." (PMID 40963562, 2025). "Furthermore, previous studies indicated that IL6 can activate Stat3 to modulate the promoter activity of FGL1 in hepatocellular carcinoma (HCC)." (PMID 39085849, 2024). "Interestingly, together with an inhibitor treatment, the IL-6 levels were no longer significantly increased, which is beneficial because elevated IL-6 serum levels can be considered as a precursor for serious hepatic diseases, such as hepatocellular carcinoma." (PMID 38672139, 2024). "Experimental studies using a diethylnitrosamine-induced hepatocellular carcinoma model have demonstrated that IL-6 promotes compensatory proliferation of hepatocytes, and its absence or inhibition of IL-6 receptor-related proteins impedes liver tumor development." (PMID 38304429, 2024). "Similarly, irradiation of hepatoma cells has been linked to the secretion of tumor necrosis factor-alpha (TNF-α), IL-6, VEGF, epidermal growth factor (EGF), MMP2, and MMP9, all of which enhance tumor invasion." (PMID 39759518, 2024). "Moreover, PTPRO-mediated autophagy inhibits tumorigenesis in hepatocellular carcinoma (HCC), and PTPRO downregulation is associated with an IL-6-driven increase in PD-L1 expression in monocytes and macrophages." (PMID 38182570, 2024). "The levels of PD1 + TIM3 + T/T, TIGIT + T/T, and IL-6 after 2 cycles of immunotherapy may serve as predictors of treatment efficacy in patients with hepatocellular carcinoma." (PMID 38110467, 2023). "Interestingly, recent studies in hepatocellular carcinoma showed that PGRMC1 activated the NF-kB pathway to promote the release of Interleukin-6." (PMID 37887342, 2023). "As it is, HBX has been shown to increase IL-6 expression in hepatoma cells." (PMID 37446321, 2023). "Similarly, a clinical observational study also reported decreased levels of circulating TNF-α and IL-6 in hepatocellular carcinoma (HCC) patients after Lenvatinib treatment." (PMID 36839733, 2023). "In addition, IL-6 induced proliferation in hepatocellular carcinoma cell lines which was attenuated by TGF-β26." (PMID 37533959, 2023). "Additionally, the variant rs2267401 has been shown to increase gallbladder cancer and hepatocellular carcinoma risk, likely by increased APOBEC3B expression that arises through heightened promoter activity and IL-6 response." (PMID 36978147, 2023). "Thus, in this study, various lymphocyte subpopulations expressing immunosuppressive receptors and IL-6 were selected as predictors of efficacy in hepatocellular carcinoma patients receiving immunotherapy." (PMID 38110467, 2023). "Collectively, the research suggests that IL-6 could potentially serve as a biomarker indicating the response to cabozantinib treatment in patients with hepatocellular carcinoma." (PMID 37892997, 2023). "Interestingly, the opposite effect was observed in the H22 murine model of HCC, possibly due to significant upregulation of IDO (Indoleamine 2,3-dioxygenase) and IL-6 by infected hepatocellular carcinoma cells." (PMID 37974615, 2023). "Likewise, by blocking the IL6/STAT3 signaling pathway, morusin caused apoptosis and prevented angiogenesis in hepatocellular cancer cells." (PMID 37228582, 2023). "Likewise, in hepatocellular carcinoma, CAFs recruit normal DCs and induce their differentiation into regulatory DCs(RDCs) and dysfunctional DCs by activating the IL-6-mediated STAT3 pathway." (PMID 36759842, 2023). "In human hepatoma cells, IL-6 up-regulated hepcidin, which was inhibited by NOG." (PMID 35204186, 2022).